NUP85 (nucleoporin 85)
Description:
Essential component of the nuclear pore complex (NPC) that seems to be required for NPC assembly and maintenance. As part of the NPC Nup107-160 subcomplex plays a role in RNA export and in tethering NUP96/Nup98 and NUP153 to the nucleus. The Nup107-160 complex seems to be required for spindle assembly during mitosis. NUP85 is required for membrane clustering of CCL2-activated CCR2. Seems to be involved in CCR2-mediated chemotaxis of monocytes and may link activated CCR2 to the phosphatidyl-inositol 3-kinase-Rac-lammellipodium protrusion cascade. Involved in nephrogenesis.
Synonyms: NUP75; FLJ12549; FROUNT; NPHS17
Tractability: PROTAC: ubiquitination databases record sites on it; its protein half-life has been measured.
Gene: Protein-coding gene on chromosome 17 (75,205,659 to 75,235,758, forward strand). Ensembl gene ENSG00000125450.
Subcellular location: Nucleus, nuclear pore complex; Chromosome, centromere, kinetochore; Cytoplasm, cytoskeleton, spindle; Cytoplasm; Nucleus membrane
Subcellular location (Human Protein Atlas): Nucleoplasm; Actin filaments; Basal body; Cytosol; Vesicles
Pathways (Reactome):
Disease: Defective TPR may confer susceptibility towards thyroid papillary carcinoma (TPC); HCMV Early Events; HCMV Late Events; NEP/NS2 Interacts with the Cellular Export Machinery; NS1 Mediated Effects on Host Pathways; Nuclear import of Rev protein; Rev-mediated nuclear export of HIV RNA; SARS-CoV-2 activates/modulates innate and adaptive immune responses; Transport of Ribonucleoproteins into the Host Nucleus; Viral Messenger RNA Synthesis; Vpr-mediated nuclear import of PICs
Cell Cycle: Amplification of signal from unattached kinetochores via a MAD2 inhibitory signal; EML4 and NUDC in mitotic spindle formation; Mitotic Prometaphase; Nuclear Pore Complex (NPC) Disassembly; Postmitotic nuclear pore complex (NPC) reformation; Resolution of Sister Chromatid Cohesion; Separation of Sister Chromatids
Metabolism of RNA: Transport of Mature mRNA Derived from an Intronless Transcript; Transport of Mature mRNA derived from an Intron-Containing Transcript; Transport of the SLBP Dependant Mature mRNA; Transport of the SLBP independent Mature mRNA; snRNP Assembly; tRNA processing in the nucleus
Metabolism of proteins: SUMOylation of DNA damage response and repair proteins; SUMOylation of DNA replication proteins; SUMOylation of RNA binding proteins; SUMOylation of SUMOylation proteins; SUMOylation of chromatin organization proteins; SUMOylation of ubiquitinylation proteins
Metabolism: IP3 and IP4 transport between cytosol and nucleus; IP6 and IP7 transport between cytosol and nucleus; IPs transport between nucleus and cytosol; Regulation of Glucokinase by Glucokinase Regulatory Protein
Cellular responses to stimuli: Regulation of HSF1-mediated heat shock response
Immune System: ISG15 antiviral mechanism
Signal Transduction: RHO GTPases Activate Formins
Gene Ontology:
Molecular function: protein binding; structural constituent of nuclear pore
Biological process: nephron development; nucleocytoplasmic transport; positive regulation of DNA-templated transcription; protein import into nucleus
Cellular component: cytoplasm; cytosol; kinetochore; membrane; nuclear envelope; nuclear membrane; nuclear pore outer ring; nucleoplasm; nuclear pore; spindle
Genetic constraint (gnomAD): Loss-of-function variants: 22 observed, 89.27 expected, observed/expected ratio (o/e) 0.25, 90% interval 0.17 to 0.35. The upper end of that interval is the gene's LOEUF score, 0.35, which puts it in group 1 of 6, group 1 being the genes least tolerant of losing a copy. Missense variants: 722 observed, 808.94 expected, observed/expected ratio (o/e) 0.89, 90% interval 0.84 to 0.95. Synonymous variants: 301 observed, 302.81 expected, observed/expected ratio (o/e) 0.99, 90% interval 0.9 to 1.09.
Homologues: Orthologues: macaque NUP85 (97% identical), dog NUP85 (92% identical), mouse Nup85 (92% identical), pig NUP85 (91% identical), chimpanzee NUP85 (90% identical), rat Nup85 (88% identical), rabbit NUP85 (86% identical), tropical clawed frog nup85 (68% identical), zebrafish nup85 (39% identical), Drosophila melanogaster Nup75 (31% identical), zebrafish NUP85 (26% identical), Caenorhabditis elegans npp-2 (20% identical).
Diseases named in the same sentence as NUP85 in open-access papers:
NUP85 is named in the same sentence as 40 diseases in open-access papers, as found by Europe PMC text mining. Sharing a sentence is not in itself a finding about the gene and the disease. The quoted sentences say what the papers report.
HIV-1 infection (2 papers, 2018 to 2024). The type species of lentivirus and the etiologic agent of acquired immunodeficiency syndrome (AIDS). "Moreover, some Nup depletions (SEH1, NUP85, NUP160, SEC13, NUP98, NUP107, ELYS/ACHTF1, NUP93, NUP205, NUP88, and NUP214) that reduced both HIV-1 infection and MX2 activity in dividing HeLa cells, affected MX2 activity but not HIV-1 infection in non-dividing HeLa cells." (PMID 30084827, 2018).
liver diseases (2 papers, 2024 to 2026). "Nuclear pore protein 85 (NUP85) has been implicated in the development of various liver diseases." (PMID 41903125, 2026). "Notably, structure of nucleoporin 85 (NUP85) is related to lipid metabolism and inflammation of liver diseases." (PMID 38617542, 2024).
microcephaly (2 papers, 2023). A congenital or acquired developmental disorder in which the circumference of the head is smaller than normal for the person's age and sex. "Concurrently, mutations affecting the interaction of the NUP85 protein with cytoskeletal proteins and components of mitotic machinery during brain developmental stages led to a neurological phenotype including microcephaly, developmental delay, and epilepsy." (PMID 38136965, 2023). "Our report describes a novel NPHS17-related compound heterozygous NUP85 variant associated with microcephaly, severe epileptic encephalopathy, and severe neurological impairment, expanding the phenotype including SRNS and neurologic disease." (PMID 38136965, 2023). "Interestingly, biallelic mutations in NUP85 have also been associated with a neurodevelopmental disorder characterized by microcephaly, developmental delay, epilepsy, agenesis of the corpus callosum, and dysmorphic features." (PMID 38136965, 2023). "Among them, NUP85 was linked to childhood-onset steroid-resistant nephrotic syndrome (SRNS) in four affected individuals with intellectual disability but no microcephaly." (PMID 36846113, 2023). "Two families carried different homozygous pathogenic NUP85 variants associated with SRNS without microcephaly and brain defects, and one carried two compound heterozygous pathogenic NUP85 variants; notably, two siblings from the latter family showed SRNS and ID without brain abnormalities." (PMID 38136965, 2023).
nephrotic syndrome (2 papers, 2022 to 2025). A collection of symptoms that include severe edema, proteinuria, and hypoalbuminemia; it is indicative of renal dysfunction. "NUP85 is related to the composition of the Nup107–160 subunit of the nuclear pore complex, mostly associated with nephrotic syndrome." (PMID 36452490, 2022).
pancreatic cancer (2 papers, 2011 to 2021). "It has been reported that targeting NUP85 in pancreatic cancer cells inhibits their invasiveness and metastasis." (PMID 33663535, 2021).
chronic myeloid leukemia (1 paper, 2021). "To generate hypomorphic alleles of essential genes, we first sought to confirm the essentiality of candidates NUP58, NUP153, and NUP85 in the human chronic myeloid leukemia near‐haploid cell line HAP1." (PMID 34528284, 2021).
colorectal adenocarcinoma (1 paper, 2025). The most common type of colorectal carcinoma. "It was found that elevated expression of RPL31, CCT2, RPL17, and NUP85, as well as downregulation of NUP98, CDC37, DNM2, and SNRPN resulted from corresponding μ-ASOs treatment, correlating with improved survival in colorectal adenocarcinoma patients according to the TCGA database." (PMID 41373892, 2025).
glioma (1 paper, 2025). A benign or malignant brain and spinal cord tumor that arises from glial cells (astrocytes, oligodendrocytes, ependymal cells). "Alb/LF NPs encapsulating DDC/Cu-Fe facilitate brain accumulation, where DDC/Cu-Fe cooperatively induces glioma cell ferroptosis through oxidative stress, activates T cell immunity, and suppresses TAMs by FROUNT (also known as NUP85) inhibition." (PMID 40717985, 2025).
hepatocellular carcinoma (1 paper, 2021). A malignant tumor that arises from hepatocytes.
liver fibrosis (1 paper, 2026). "The expression level of NUP85 was found to be elevated in the liver tissues of liver fibrosis patients and mice." (PMID 41903125, 2026). "The present study aimed to explore the role of NUP85 in liver fibrosis." (PMID 41903125, 2026). "Furthermore, we developed a CREKA-coupled liposome as a targeted delivery system to deliver Mogroside V (MV), a pharmacological inhibitor of NUP85, to activated HSCs and attenuate liver fibrosis." (PMID 41903125, 2026). "Taken together, the present study demonstrated that NUP85 is a novel regulator of liver fibrosis and that the NUP85-USP47-ASK1 signaling pathway might be a strategy for therapeutic intervention." (PMID 41903125, 2026).
metastatic prostate carcinoma (1 paper, 2025). A carcinoma that arises from the prostate gland and has spread to other anatomic sites. "In addition, elevated levels of other NUPs downregulated by bromoxib in TPP (i.e., NUP188, NUP210, NUP85, NUP62, and NUP214) were identified in metastatic prostate cancer, suggesting that NPC dysregulation may drive aggressive cancer phenotypes." (PMID 40137294, 2025).
nonalcoholic steatohepatitis (1 paper, 2024). "Similarly, blockade of Nup85 attenuates steatosis and monocyte recruitment caused by macrophage chaperone-mediated autophagy deficiency in nonalcoholic steatohepatitis (NASH) mice." (PMID 39080077, 2024).
primary autosomal recessive microcephaly (1 paper, 2024). "Recently, biallelic and heterozygous human NUP85 variants were found in primary autosomal recessive microcephaly and Seckel syndrome spectrum disorders (MCPH–SCKS)." (PMID 39080077, 2024).
Seckel syndrome (1 paper, 2023). A rare autosomal recessive inherited syndrome caused by mutations in the ATR gene, RBBP8 gene, CENPJ gene, CEP152 gene, CEP63 gene, NIN gene, DNA2 gene, or TRAIP gene. "Recently, we broaden the phenotype spectrum of NUP85-associated disease by reporting NUP85 variants in two unrelated individuals with primary autosomal recessive microcephaly (MCPH) and Seckel syndrome (SCKS) spectrum disorders (MCPH-SCKS) without SRNS." (PMID 36846113, 2023). "In this study, we report compound heterozygous NUP85 variants in an index patient with only MCPH phenotype, but neither Seckel syndrome nor SRNS was reported." (PMID 36846113, 2023).
virus infection (1 paper, 2022). "We observed a gradual decrease in NUP85 mRNA level in the process of each virus infection, and the level decreased by half at 12 h.p.i." (PMID 36051755, 2022). "Still, we failed it as the cells became too unwell to do viral infection after NUP85 introduction either by transient transfection or by lentivirus transduction." (PMID 36051755, 2022).
tumor (10 papers, 2019 to 2025). "NUP85 regulated macrophages to affect liver inflammation 38, and NUP85 was very important in the progress of tumor genesis." (PMID 38617542, 2024). "Moreover, a recent study demonstrated that DSF combined with an anti-PD-1 Ab synergistically suppressed tumor growth by targeting FROUNT (also known as NUP85) function and elevated the number of CD8+ T cells in the tumors." (PMID 34858816, 2021). "Besides, targeting NUP85 with disulfiram could inhibit macrophage accumulation and its tumor-promoting characteristics." (PMID 36034466, 2022). "In addition, NUP85, HAX1, GNPDA1 and HDLBP exhibited elevated mRNA expression levels in GI tumor tissues when compared to the adjacent non-tumor tissues, whereas GPD1 expression was suppressed in GI tumor tissues compared to the non-tumor tissues." (PMID 33663535, 2021). "The NUP85, HAX1, GNPDA1 and HDLBP protein levels were significantly elevated in tumor tissues compared to normal samples, while GPD1 was significantly down-regulated in tumor tissues." (PMID 33663535, 2021).
cancer (8 papers, 2015 to 2025). A tumor composed of atypical neoplastic, often pleomorphic cells that invade other tissues. "In summary, we identified and validated a glycolysis associated five-gene risk signature (NUP85, GPD1, HAX1, GNPDA1 and HDLBP) that can predict the OS of GI Asian cancer patients." (PMID 33663535, 2021). "It is also found in direct or indirect interactions with numerous known cancer genes, such as NBR1, BRACA1, ICT1, SUMO, NUP85 and others." (PMID 31142264, 2019).
infection (6 papers, 2014 to 2025). The state of being infected such as from the introduction of a foreign agent such as serum, vaccine, antigenic substance or organism. "Nup85 associates with RNP subunits PB1/PB2 in an RNA-dependent manner during infection." (PMID 40508167, 2025). "The NP vRNA in the cytoplasm in the NUP85 knockdown cells was only 23% compared to that in the control cell at 6 h post-infection." (PMID 36051755, 2022). "And the total vRNA in the nucleus and cytoplasm decreased by 45% in the NUP85 knockdown cells compared to that in the control cells at 6 h post-infection, and it decreased by 60% in the NUP85 knockdown cells at 12 h post-infection." (PMID 36051755, 2022). "To investigate NUP85 expression during IAV infection, we detected the mRNA and protein levels of NUP85 in A549 cells after infection with three strains of IAV (influenza A H1N1 PR8, H3N2 HZ163, H9N2 JSC1), respectively." (PMID 36051755, 2022). "The NP vRNA in the nucleus in the NUP85 knockdown cells was only around a half when compared with the control cell at 6 and 12 h post-infection." (PMID 36051755, 2022). "Knockdown of NUP85 significantly delayed vRNP entry into the nucleus at 3 h post-infection, inhibiting polymerase activity and suppressing viral replication." (PMID 36051755, 2022). "The result showed much less viral NS1 protein was detected in the cells with NUP85 siRNA treatment compared with NC siRNA treatment at different time points post-infection by three different strains of viruses." (PMID 36051755, 2022). "In previous research, it has been shown that legume mutants deficient in the Nod factor signalling pathway such as castor, ccamk and nup85 exhibit root hair branching in an infection- or Nod factor treatment-dependent manner." (PMID 31828682, 2020). "However, compared with NUP85 knockout mice, this method has some limitations in the variable infection rate and efficiency of NUP85 knockout." (PMID 38617542, 2024). "To further confirm the defective nuclear import of vRNP when NUP85 was knocked down, we fractionated the cytoplasm and nucleus of infected cells and examined vRNP distribution indicated by NP expression at 3, 6, and 9 h post-infection by Western blot." (PMID 36051755, 2022). "The mRNA level of NUP85 was detected by qRT-PCR at different time points post-infection." (PMID 36051755, 2022). "But we did not see any difference in the mRNA levels of multiple immune-related factors in the NUP85 siRNA and NC siRNA-treated A549 cells after influenza A virus JSC1 H9N2 infection." (PMID 36051755, 2022). "Mutants defective for either of the common symbiosis genes SYMRK, CASTOR, POLLUX, NENA, NUP85, or NUP133 produce very similar phenotypes in symbiosis, in that they abort infection at the epidermis and are impaired in calcium-spiking, which placed them at the same hierarchical level." (PMID 25422918, 2014). "We observed that NUP98 protein levels were decreased both in SupT1 and HEK293T cell types upon HIV-1 NL4.3 infection by 4.7- and 1.5-fold, respectively (respectively), whereas the protein levels of other NUPs such as NUP62, NUP155, NUP133, NUP107, and NUP85 remained unaffected." (PMID 38449868, 2024). "Furthermore, unlike during infection, we observed downregulation of the protein levels of NUP62 and NUP85 by 1.2- and 2.1-fold, respectively, whereas NUP133 was upregulated by 1.5-fold." (PMID 38449868, 2024).
GI tumor (1 paper, 2021). "We identified five novel glycolysis-associated genes (NUP85, GPD1, HAX1, GNPDA1, and HDLBP) in GI tumor and normal tissues." (PMID 33663535, 2021).
NUP85 also shares sentences with these, for which no sentence is quoted: alcoholism (3 papers); amnesia (1); Anosmia (1); Anxiety (1); Autoimmunity (1); congenital microcephaly (1); COVID-19 (1); developmental delay (1); end-stage renal disease (1); endometrial carcinoma (1); epilepsy (1); Epileptic encephalopathy (1); glomerulopathy (1); Intellectual disability (1); lung carcinoma (1); melanoma (1); myopathy (1); nephritis (1); neurologic disease (1); nonalcoholic fatty liver disease (1); steroid-resistant nephrotic syndrome (1).